PDGFB (platelet derived growth factor subunit B)
Diseases named in the same sentence as PDGFB in open-access papers (continued):
Sharing a sentence is not in itself a finding about the gene and the disease.
dermatofibrosarcoma protuberans (41 papers, 2011 to 2025). Dermatofibrosarcoma protuberans (DFSP) is a rare infiltrating soft tissue sarcoma, generally of low grade malignancy, arising from the dermis of the skin and characteristically associated with a specific chromosomal translocation t(17;22). "Among them, COL1A1::PDGFB fusion uterine sarcoma is a recently described entity that shares the same genetic alteration as dermatofibrosarcoma protuberans (DFSP)." (PMID 41463261, 2025). "In the dermatofibrosarcoma protuberans, the fusion of the collagen type I alpha 1 (COL1A1) gene with the PDGFB gene caused PDGFBB and its receptor (PDGFRβ) autocrine stimulation and cell proliferation." (PMID 38378786, 2024). "Reverse transcription PCR (RT-PCR) of the tumor tissue revealed gene fusion between exon 25 of COL1A1 and exon 2 of PDGFB; thus atrophic dermatofibrosarcoma protuberans was diagnosed." (PMID 26932148, 2016). "The relevance of these observations is supported by the fact that human dermatofibrosarcoma protuberans, skin tumors arising from constitutive PDGFB production with little aggressiveness, also display some senescence hallmarks." (PMID 23934686, 2013). "Biopsy confirmed a dermatofibrosarcoma with PDGFB rearrangement." (PMID 40641635, 2025). "In addition, we previously found a case of dermatofibrosarcoma protuberans that was positive for novel COL1A1 exon 14/PDGFB fusion." (PMID 28978917, 2017). "More than 90% of all cases of dermatofibrosarcoma protuberans (DFSP) contain a translocation of the Collagen alpha-1(I) chain (COL1A1) with PDGFB, often in a supernumerary ring chromosome." (PMID 38611033, 2024). "In dermatofibrosarcoma protuberans (DFSP), the growth factor platelet-derived growth factor B (PDGFB) is constitutively activated by the collagen, type I, alpha 1 (COL1A1) promoter in chromosome 17." (PMID 22665999, 2012). "Pigmented dermatofibrosarcoma protuberans (DFSP): DFSP typically shows storiform spindle cell proliferation and is characterized by COL1A1: PDGFB fusion." (PMID 41409361, 2025). "Since this finding, PDGF ligand dysregulation has been described in several human cancers, including glioblastoma and the rare skin tumour dermatofibrosarcoma protuberans (DFSP) where a chromosomal translocation event between PDGFB and collagen 1A1 results in a tumour promoting PDGF‐like protein." (PMID 33411331, 2021). "Roneparstat counteracted the autocrine loop induced by the COL1A1/PDGFB fusion oncogene, expressed in a human dermatofibrosarcoma protuberans primary culture and in NIH3T3COL1A1/PDGFB transfectants, inhibiting cell anchorage-independent growth and invasion." (PMID 27374103, 2016). "Hyalinized zones with “cracking” artifacts mimicking giant cell fibroblastoma have also been observed, and the absence of a PDGFB gene rearrangement in these areas argues in favor of an FHI." (PMID 34449590, 2021). "The partial amplification pattern might be compatible with fusion of the involved genes, similar to cases described in dermatofibrosarcoma protuberans, with COL1A1::PDGFB or in case of EWSR1::NFATC2 fusion (EWSR1 pattern of FISH) in round cell sarcomas with EWSR1–non-ETS fusions." (PMID 39839837, 2024). "Noteworthy, dermatofibrosarcoma protuberans (DFSP), a rare STS subtype with a local infiltrative growth pattern, carries a COL1A1/PDGFB fusion-gene that is responsible for PDGFRβ autocrine activation and subsequent tumorigenesis." (PMID 32532153, 2020). "We also examined the presence of chromosomal rearrangements including in the PDGFB gene, because the fusion gene leads to autocrine PDGF receptor stimulation in dermatofibrosarcoma protuberans (DFSP)." (PMID 23642185, 2013).
breast carcinoma (28 papers, 2013 to 2024). "In the paclitaxel-resistant cells, the most highly upregulated genes included ones that have been associated with breast cancer metastasis, such as the platelet-derived growth factor PDGFB and the MYB oncogene." (PMID 38999963, 2024). "In addition, PDGFB/PDGFRβ were found to be highly expressed in many subtypes of breast cancer cells and tissues, and breast cancer-associated stromal cells and vasculature also exhibited positive staining of PDGFB/PDGFRβ." (PMID 35672821, 2022). "The mRNA expression levels for eight pro-angiogenic genes [VEGFA, HGF, FGF1, FGF2, ANGPT1, ANGPT2, PDGFA, and PDGFB] were obtained from the METABRIC (Molecular Taxonomy of Breast Cancer International Consortium) dataset available at cBioPortal public domain." (PMID 39302921, 2024). "Previous study showed that PDGFB promoter was activated in breast cancer cells by HIF1α under hypoxia." (PMID 34470658, 2021). "Next, we examined if PDGFB and IL1β expression are predictive of primary ER+ breast cancer prognosis using SurvExpress online database." (PMID 31419632, 2019). "The cytokine secretory phenotype of MDA-MB-231LN breast cancer cells with altered AF1q expression revealed changes in expression of platelet-derived growth factor subunit B (PDGF-B)." (PMID 27259262, 2016). "PDGFB/PDGFR-β axis is well documented as a vital oncogenic signal and potential therapeutic target for different types of carcinomas, such as prostate cancer, pancreatic cancer, and breast cancer." (PMID 35672821, 2022). "We found similar results when PDGFRβ was analyzed across breast cancer patients irrespective of subtypes and expression of its ligand PDGFB in chemotherapy treated patients." (PMID 30777101, 2019). "Interestingly, some of these genes have also been linked to cancer progression, for example HIF1A-dependent upregulation of PDGFB and ANGPTL-4 promotes metastasis of hypoxic breast cancer cells." (PMID 28077088, 2017).
liver fibrosis (24 papers, 2008 to 2025). "The selection was either based on significant regulation among the list of CEC-associated genes, relation to liver fibrosis [Gata4, Myc, platelet-derived growth factor subunit B (Pdgfb)], or established LSEC angiocrine factors." (PMID 34658910, 2021). "Prior research has established that hepatocyte-specific overexpression of PDGFB can induce liver fibrosis." (PMID 40393967, 2025). "Whereas transgenic expression of PDGFB in the liver under albumin promoter increased collagen deposition and promoted CCl4-induced liver fibrosis, ablation of PDGFRβ in HSCs attenuated liver fibrosis." (PMID 37860002, 2023). "In TGF‐β1‐treated HLOs, receptor‐ligand expression was observed involving PDGFB and PDGFRB, recapitulating an important hallmark of liver fibrosis in vivo." (PMID 37962490, 2023). "In addition, our MASH EVs were significantly enriched with several ligands that are crucial in mediating liver fibrosis, including PDGFB, LTBP1 and TIMP3." (PMID 40313415, 2025). "This prompts further investigation into whether Metrnl can modulate PDGFB levels, a ligand for PDGFRβ that activates HSCs and contributes to liver fibrosis." (PMID 40393967, 2025). "The main active isoform PDGFB is produced by aHSCs and infiltrating macrophages, and the overexpression of PDGFB in mice has been found to induce HSC activation and liver fibrosis." (PMID 33807461, 2021). "HQD down-regulated the expressions of PDGFra, PDGFrb, PDGFb, PDGFd, COL1A1, COL1A2, COL5A2 and THBS1, and TGF-β and PDGF signaling pathways in the DMN-induced liver fibrosis in rats." (PMID 26691002, 2015). "Ten DEGs including PDGFra, PDGFrb, PDGFb, PDGFd, COL1A1, COL1A2, COL5A2, ITGA5, THBS1 and IL1R1, closely related to liver fibrosis, were chosen for the real-time qRT-PCR analysis." (PMID 26691002, 2015). "PDGFB is a profibrotic cytokine that results in HSC activation and liver fibrosis." (PMID 39453386, 2024). "PDGFB and TGFB are well-established drivers of liver fibrosis." (PMID 39656528, 2024). "Our results indicate that p38 MAPK or GSK3β kinase inhibitors can block liver fibrosis irrespective of whether it is driven by PDGFB or TGFB." (PMID 39656528, 2024).
glioblastoma (23 papers, 2008 to 2025). The most malignant astrocytic tumor (WHO grade IV). "Though the Nuclear factor 1 family member NFIX has been strongly implicated in PDGFB-induced glioblastoma, its molecular mechanisms of action remain unknown." (PMID 19337383, 2009). "Furthermore, the key role of PDGFB signaling in the initiation of glioblastoma has been validated in mouse models by an injection of a murine retroviral vector expressing PDGFB." (PMID 40362634, 2025). "Another identified unfavorable gene, CECR1, was demonstrated to serve a critical function in M2-like macrophages, mediating cross-talk between macrophages and pericytes in glioblastoma via paracrine PDGFB-PDGFRβ signaling, promoting pericyte recruitment and migration and tumor angiogenesis." (PMID 31781506, 2019). "Our analysis of The Cancer Genome Atlas (TCGA) glioblastoma dataset revealed a positive correlation of REIC/Dkk3 and PDGFB or PECAM1 (CD31), suggesting the role of REIC/Dkk3 in angiogenesis." (PMID 36006934, 2022). "We therefore pre-treated radiated SF188 cells with DEXA and this significantly increased the radio-protective effect of PDGFB, further supporting the idea that DEXA “primes” glioblastoma cells towards PDGFR mediated growth and survival signalling." (PMID 33478100, 2021). "We analysed gene expression of the PDGF system (PDGFA, PDGFB, PDGFC, PDGFD, PDGFRA, PDGFRB) in 36 GBMs studied on Ivy Glioblastoma Atlas Project." (PMID 29127351, 2017).
gastric cancer (14 papers, 2010 to 2024). A primary or metastatic malignant neoplasm involving the stomach. "The secretion of PDGFB by gastric carcinoma cells was associated with lymphatic metastasis." (PMID 33115518, 2020). "The expression of PDGFB has been reported to be closely related to tumor metastasis in patients with gastric cancer." (PMID 38693916, 2024). "It was reported in previous research that higher expression of PDGFB in gastric cancer promoted angiogenesis in metastases via activation of the MAPK/ERK signaling pathway in endothelial cells." (PMID 38730286, 2024). "Overexpression of PDGFB has been detected in several human malignancies including pancreatic cancer, gastric cancer, glioma, and melanoma." (PMID 35672821, 2022). "For example, gastric cancer patients with lymph node metastasis had high levels of PDGFB and PDGFRβ." (PMID 35672821, 2022). "Finally, a positive correlation between NEAT1 and TGFβR2, VEGF-A, Smad4, PDGFB was seen in GEO gastric cancer datasets GSE62254 (n = 200)." (PMID 34552925, 2021). "Besides, platelet-derived growth factor-BB (PDGFB) secretion from anoikis resistant gastric cancer cells constructs a C/EBPβ-PDGFB-PDGFRβ-MAPK feedback loop with vascular ECs, which supports angiogenesis and metastasis in gastric cancer." (PMID 36906534, 2023). "Therefore, down-regulation of PDGFB and VEGFA may explain the anti-proliferative effect exerted by DACT1α in gastric cancer cells." (PMID 27833078, 2016).
brain tumors (13 papers, 2012 to 2025). "For example, PDGF-B inhibition that causes down-regulation of miR-21 is also known to differentiate PDGFB-driven mouse brain tumor cells along the oligodendrocyte lineage." (PMID 22931209, 2012). "Both H3K27ac and RNAPII-Ser2,5p FFPE-CUTAC on RELA- and PDGFB-driven brain tumors showed much better sensitivity based on number of peaks called and much higher FRiP values than either H3K27ac CUT&Tag on frozen kidney or FACT-seq on FFPEs." (PMID 37739938, 2023). "To determine if PTN affected the histological subtype of PDGFB-induced tumors, we examined the histopathology of the brain tumors." (PMID 27806344, 2016). "PDGFB-induced brain tumor model was utilized for the validation of in vitro data." (PMID 38561856, 2024). "There was also reduced survival in PDGFB-induced brain tumors in mice when Csmd1 was downregulated." (PMID 38561856, 2024). "While future research endeavors will need to examine whether inflammatory or viral inputs engender gliomagenesis in humans by providing a constitutive source of PDGFB, our data implicate microenvironmental constituents as potentially important contributors to the initiation of brain tumors." (PMID 40060572, 2025). "To identify tumor-specific candidate regulatory elements we performed pairwise comparisons between three different mouse brain tumors (YAP1-, PDGFB- and RELA-driven tumors) and normal mouse brains." (PMID 37739938, 2023).
sarcoma (13 papers, 2011 to 2025). A usually aggressive malignant neoplasm of the soft tissue or bone. "Long shown to be expressed and active in Ewing sarcoma, PDGFRB and autocrine and paracrine feedback loops with its ligand PDGFB (platelet-derived growth factor beta) contribute to sarcoma cell proliferation and migration." (PMID 29776413, 2018). "However, most of these tumors have been recently reclassified as genetically defined tyrosine kinase fusion associated sarcomas including in particular NTRK and COL1A1::PDGFB fusions." (PMID 39196362, 2024).
COVID-19 (12 papers, 2020 to 2025). A disease caused by infection with severe acute respiratory syndrome coronavirus 2. "Our study demonstrated that the liability of AMD is associated with an increased risk of COVID-19, and PDGFB may be responsible for the severe COVID-19 outcomes among AMD patients." (PMID 36614910, 2022). "In our study, we found a dysregulation of cytokines such as IL-1RA, TNF-α, IP-10, and PDGFb, which are elevated in combination in the plasma of COVID-19 patients in other studies and correlate with disease severity." (PMID 38791465, 2024). "A recent study found that lower levels of PDGFb in the serum of COVID-19 patients compared to healthy controls within the first 24 h of hospitalization predict mortality." (PMID 38791465, 2024). "This is consistent with a previous study that found decreased serum PDGFb levels in COVID-19 patients compared to controls." (PMID 38791465, 2024). "The growth factor PDGFB presented a trend toward a decrease in concentration comparing patients with mild disease and those who would die from COVID-19." (PMID 36700209, 2022). "As PDGFb participates in tissue repair and angiogenesis, our results may indicate that COVID-19 might be inducing vascular tissue damage in our patients." (PMID 38791465, 2024). "However, NOS and PDGFB are upregulated in the oligodendrocytes of COVID-19 patients’ brains compared to the healthy control." (PMID 37239234, 2023). "However, other studies have found increased plasma levels of PDGFb in COVID-19 patients." (PMID 38791465, 2024). "Our finding of significantly higher PDGFB expression among COVID-19 patients ages 40 years and older in the middle stage (11–21 days after the symptom onset) compared to the early stage (0–10 days) is consistent with the observation that COVID-19 symptoms peak 10 days after symptom onset." (PMID 36614910, 2022). "Further, the expression of genes involved in endothelial dysfunction, namely CCL2, PDGFRA, PDGFB, and PDGFC, is found to be increased in ACE2-positive brain cells of COVID-19 patients." (PMID 37239234, 2023). "We evaluated various omics data to identify possible functional links between PDGFB and AMD and COVID-19 outcomes." (PMID 36614910, 2022). "Significantly up-regulated levels of cytokines and chemokines including IL1-β, IL1RA, IL10, IL9, IL8, IL7, basic FGF2, GCSF, GMCSF, IFNγ, IP10, MCP1, MIP1α, MIP1β, PDGFB, TNFα, and VEGFA in blood, have been confirmed in COVID-19 patients." (PMID 33041797, 2020). "Additionally, the expression of genes associated with endothelial dysfunction—namely CCL2, PDGFRA, PDGFB, and PDGFC—was also found to be increased in ACE2-positive brain cells of COVID-19 patients." (PMID 37239234, 2023). "These collective findings suggest that lowering PDGFB expression and serum PDGF-BB concentration may reduce the severity of COVID-19, particularly among older people." (PMID 36614910, 2022). "Moreover, the PDGFB-EGFR and TUBB1C/2B/3 proliferation signaling pathways are also predicted as the COVID-19 related signaling pathways." (PMID 33413329, 2021). "Although we did not observe significantly different PDGFB expression between COVID-19 patients and COVID-19-free controls, recent studies showed significantly higher serum PDGF-BB concentration in COVID-19 patients compared to the controls." (PMID 36614910, 2022).
melanoma (12 papers, 2015 to 2025). A malignant, usually aggressive tumor composed of atypical, neoplastic melanocytes. "This dysregulated immune microenvironment characterized by abnormal PDGFB signaling and the presence of CAFs is likely responsible for the unfavorable prognosis and suboptimal response to immunotherapy observed in melanoma." (PMID 38233802, 2024). "They highlight the potential of targeting EPHA3, PDGFB signaling, and the modulation of pericyte-CAFs transition as promising strategies for developing novel therapeutic interventions and improving patient outcomes in melanoma." (PMID 38233802, 2024). "To uncover the contribution of EC‐autophagy in regulating immunosurveillance in melanoma, we crossed the inducible PDGFb‐creERT2Rosa26tdTomato/tdTomatoline with Atg5fl/fl mice to delete the essential autophagy gene Atg5 from blood ECs (i.e., Atg5BECKO) upon tamoxifen administration." (PMID 38009521, 2023). "It has been reported that VEGFC knockdown results in reduced PDGFB levels in melanoma cell lines." (PMID 34277450, 2021). "Of note, HH044 treatment significantly reduced the expression of EDN1, PDGFB, and MMP9, which are known to facilitate melanoma disease progression and serve as druggable targets for pharmacotherapy." (PMID 40574005, 2025). "(A) Overexpression of SATB2 with TETon (iSATB2) in normal human epidermal melanocytes (HEMA-LP) and in SKMEL2, SKMEL28, and A375 melanoma cells is sufficient to induce transcriptional activation of SOX10, SNAI1/2, PDGFB, and SEMA3F mRNA." (PMID 33527896, 2021). "Similarly, MITF and BPTF co-repress SASP genes like SERPINE1, IL24, PDGFB, and CYR61 as well as ZEB1 that has a crucial role in melanoma progression." (PMID 26440048, 2015).
atherosclerosis (11 papers, 2010 to 2024). A disease characterized by the build-up of fatty material and calcium deposition in the arterial wall resulting in partial or complete occlusion of the arterial lumen. "PDGFB stimulates cell proliferation, survival and migration, hence PDGFB upregulation has been associated to pathological angiogenesis, fibrotic conditions and atherosclerosis." (PMID 34200613, 2021). "Previous studies have indicated a potential connection between plasma levels of Dickkopf-1 (DKK1) and platelet-derived growth factor subunit-B (PDGF-B) with the development of atherosclerosis." (PMID 38175715, 2024). "PDGFB can participate in the development of intimal hyperplasia and atherosclerosis after injury." (PMID 39720896, 2024). "With the exception of one study in an African population, there have been no analyses of PDGFB polymorphisms in the context of atherosclerosis." (PMID 27835972, 2016). "Growth factors such as bFGF, EGF, IGF-1, PDGFB, TGF-β1 and VEGF-A play important roles in VSMC and EC migration and proliferation, therefore playing important roles in the pathogenesis of atherosclerosis." (PMID 27835972, 2016).